ANGPTL3 (angiopoietin like 3)
Description:
Acts in part as a hepatokine that is involved in regulation of lipid and glucose metabolism. Proposed to play a role in the trafficking of energy substrates to either storage or oxidative tissues in response to food intake (By similarity). Has a stimulatory effect on plasma triglycerides (TG), which is achieved by suppressing plasma TG clearance via inhibition of LPL activity. The inhibition of LPL activity appears to be an indirect mechanism involving recruitment of proprotein convertases PCSK6 and FURIN to LPL leading to cleavage and dissociation of LPL from the cell surface; the function does not require ANGPTL3 proteolytic cleavage but seems to be mediated by the N-terminal domain, and is not inhibited by GPIHBP1. Can inhibit endothelial lipase, causing increased plasma levels of high density lipoprotein (HDL) cholesterol and phospholipids. Can bind to adipocytes to activate lipolysis, releasing free fatty acids and glycerol. Suppresses LPL specifically in oxidative tissues which is required to route very low density lipoprotein (VLDL)-TG to white adipose tissue (WAT) for storage in response to food; the function may involve cooperation with circulating, liver-derived ANGPTL8 and ANGPTL4 expression in WAT (By similarity). May stimulate hypothalamic LPL activity (By similarity). [ANGPTL3(17-221)]: In vitro inhibits LPL activity; not effective on GPIHBP1-stabilized LPL. Involved in angiogenesis. Binds to endothelial cells via integrin alpha-V/beta-3 (ITGAV:ITGB3), activates FAK, MAPK and Akt signaling pathways and induces cell adhesion and cell migration. Secreted from podocytes, may modulate properties of glomerular endothelial cells involving integrin alpha-V/beta-3 and Akt signaling. May increase the motility of podocytes. May induce actin filament rearrangements in podocytes implicating integrin alpha-V/beta-3 and Rac1 activation. Binds to hematopoietic stem cells (HSC) and is involved in the regulation of HSC activity probably implicating down-regulation of IKZF1/IKAROS (By similarity).
Synonyms: ANG-5; ANGPT5; ANL3; FHBL2
Tractability: Antibody: an approved drug acts on it; UniProt places it where antibodies can reach, with high confidence; its Gene Ontology location is reachable by antibodies, with high confidence; UniProt predicts a signal peptide or a membrane-spanning region. PROTAC: its protein half-life has been measured.
Gene: Protein-coding gene on chromosome 1 (62,597,464 to 62,607,196, forward strand). Ensembl gene ENSG00000132855.
Subcellular location: Secreted; Cell projection, lamellipodium
Pathways (Reactome):
Signal Transduction: NR1H2 & NR1H3 regulate gene expression linked to lipogenesis
Transport of small molecules: Assembly of active LPL and LIPC lipase complexes
Gene Ontology:
Molecular function: growth factor activity; integrin binding; lipase binding; lipase inhibitor activity; phospholipase inhibitor activity; enzyme inhibitor activity
Biological process: acylglycerol homeostasis; cell-matrix adhesion; cholesterol homeostasis; cholesterol metabolic process; fatty acid metabolic process; glycerol metabolic process; lipid homeostasis; lipid storage; negative regulation of very-low-density lipoprotein particle remodeling; phospholipid catabolic process; phospholipid homeostasis; phospholipid metabolic process; positive regulation of angiogenesis; positive regulation of cell migration; positive regulation of lipid catabolic process; regulation of chylomicron remodeling; regulation of triglyceride transport; signal transduction; triglyceride homeostasis; artery morphogenesis; integrin-mediated signaling pathway; response to hormone
Cellular component: cell surface; extracellular region; extracellular matrix; early endosome; Golgi apparatus; lamellipodium
Genetic constraint (gnomAD): Loss-of-function variants: 35 observed, 38.38 expected, observed/expected ratio (o/e) 0.91, 90% interval 0.69 to 1.21. The upper end of that interval is the gene's LOEUF score, 1.21, which puts it in group 5 of 6, group 1 being the genes least tolerant of losing a copy. Missense variants: 422 observed, 447.01 expected, observed/expected ratio (o/e) 0.94, 90% interval 0.87 to 1.02. Synonymous variants: 159 observed, 159.21 expected, observed/expected ratio (o/e) 1, 90% interval 0.88 to 1.14.
Gene-disease validity (ClinGen):
ClinGen rates the evidence that ANGPTL3 causes each of these diseases.
familial hypobetalipoproteinemia 2 (autosomal recessive): Definitive. Any hypobetalipoproteinemia in which the cause of the disease is a mutation in the ANGPTL3 gene.
Homologues: Orthologues: chimpanzee ANGPTL3 (99% identical), macaque ANGPTL3 (97% identical), dog ANGPTL3 (88% identical), rabbit ANGPTL3 (85% identical), pig ANGPTL3 (84% identical), rat Angptl3 (78% identical), mouse Angptl3 (76% identical), guinea pig ANGPTL3 (69% identical), tropical clawed frog angptl3 (52% identical), zebrafish angptl3 (44% identical). Paralogues in human: ANGPTL4 (28% identical), ANGPTL1 (27% identical), ANGPTL2 (26% identical), ANGPT1 (23% identical), ANGPT2 (23% identical), FGG (23% identical), ANGPT4 (23% identical), ANGPTL6 (22% identical), TNC (20% identical), ANGPTL5 (20% identical), TNR (20% identical), FGL2 (20% identical), and 13 more.
Diseases named in the same sentence as ANGPTL3 in open-access papers:
ANGPTL3 is named in the same sentence as 153 diseases in open-access papers, as found by Europe PMC text mining. Sharing a sentence is not in itself a finding about the gene and the disease. The quoted sentences say what the papers report.
dyslipidemia (75 papers, 2016 to 2026). "Evinacumab: Given the regulatory role of ANGPTL3, there is ongoing research to develop inhibitors of ANGPTL3 to address dyslipidemia and reduce CVD risk." (PMID 40264627, 2025). "An explorative novel approach is to target dyslipidemia using a variation of the CRISPR-Cas9 platform permanently downregulating Angptl3 by introducing non-sense mutations." (PMID 34356847, 2021). "In dyslipidemic mice, inhibition of ANGPTL3 with evinacumab, an antibody against ANGPTL3, caused a dramatic decrease in atherosclerotic lesion area and necrotic content in animal models of dyslipidemia." (PMID 34422408, 2021). "Actually, results of two large scale researches published in 2017 have manifested the inhibition ANGPTL3 by monoclonal antibody or antisense oligonucleotides can obviously influence the concentration of lipid and reduce the risk of dyslipidemia and CVD." (PMID 29334984, 2018). "Another latest report is from Stitziel and his colleagues published in 2017, which confirmed the direct relationship among ANGPTL3, dyslipidemia and the risk of CVD through three different methods." (PMID 29334984, 2018). "Due to their role in regulating LPL activity and the fact that many genome wide association studies has linked them to dyslipidemia, ANGPTL3 and 4 are being explored as drug targets for metabolic diseases." (PMID 27733177, 2016). "Observational studies have shown that increased concentrations of these proteins may reflect cardiovascular risk and suggest that treatment of patients with dyslipidemia with ANGPTL3 inhibitors may decrease the CVD risk." (PMID 34959891, 2021). "Serum ANGPTL2 and ANGPTL3 were elevated in obesity and associated with blood pressure and indices of metabolic syndrome, suggesting that they might be involved in the advancement of obesity-related hypertension and metabolic syndrome." (PMID 34422408, 2021). "Since dyslipidemia could increase the risk of CVD, drugs targeting ANGPTL3 may have considerable hope for reducing the risk of dyslipidemia, obesity and CVD." (PMID 29334984, 2018). "This part of data revealed that LOF mutation in ANGPTL3 could reduce the risk of dyslipidemia in humans probably via reducing the level of LDL-C and TG, not the levels of HDL-C." (PMID 29334984, 2018). "Two recent studies indicated that ANGPTL3 might be a promising therapeutic target in patients with dyslipidemia who are at risk of atherosclerotic cardiovascular disease." (PMID 29454388, 2018). "Therefore, ANGPTL3 inactivation may have important therapeutic implications for treatment of metabolic syndrome, type 2 diabetes, and patients in high risk of heart disease." (PMID 26754661, 2016). "The recent 2026 American College of Cardiology/American Heart Association dyslipidemia guideline emphasizes the clinical importance of targeting PCSK9, APOC3, Lp(a), and ANGPTL3." (PMID 42164756, 2026). "RNA-based therapies targeting PCSK9, Lp(a), ApoC-III, and ANGPTL3 hold transformative potential for treating dyslipidemia effectively." (PMID 39940794, 2025). "For example, Angiopoietin-like 3 (ANGPTL3) exemplifies shared biological pathways between dyslipidemia and CKD as reflected in our PheWAS findings." (PMID 41282674, 2025). "Considering the efficacy of ANGPTL3 ASO in managing dyslipidemia, assessing the safety of long-term ANGPTL3 inhibition is crucial." (PMID 38883601, 2024). "Given its role in dyslipidemia, ANGPTL3 has become one of the most promising drug targets, especially for patients who do not benefit from statins." (PMID 37634084, 2024). "The mAb and other inhibitors of ANGPTL3 have been approved by the FDA or are under clinical trials for the treatment of dyslipidemia and atherosclerosis." (PMID 37634084, 2024). "Studies in mice have shown that this state-of-the-art technology can be extended to include additional targets related to dyslipidemia such as angiopoietin-like 3 and several apolipoproteins." (PMID 38498115, 2024).
dyslipidemia (continued). "This remarkable impact of ANGPTL3 on lipid metabolism prompted interest in ANGPTL3 as a molecular target for preventing or treating dyslipidemia and CVDs." (PMID 38675122, 2024). "On the other hand, studies have also reported increased circulating levels of ANGPTL3, ANGPTL4 or ANGPTL8 in association with metabolic syndrome in cohorts with obesity, diabetes and/or dyslipidemia." (PMID 38879166, 2024). "ANGPTL3 has been identified as an interesting novel therapeutic target for the treatment of dyslipidemia." (PMID 38542527, 2024). "Similar findings have been reported in other populations, and few associations were found between ANGPTL3, ANGPTL4, or ANGPLT8 levels with features of metabolic syndrome." (PMID 38879166, 2024). "According to the lower levels of pro-atherogenic lipoprotein in these patients, ANGPTL3 can be considered as a promising therapeutic target in the treatment of dyslipidemia." (PMID 38542527, 2024). "Previously, we reported that an ANGPTL3 vaccine is a hopeful therapeutic option against dyslipidemia." (PMID 37914738, 2023). "In patients with type 2 diabetes and metabolic syndrome (Group I), ANGPTL3 and 4 levels were lower than the control group." (PMID 38140923, 2023). "Our study includes numerous such examples, supported by the recent launch of new drugs such as evinacumab, a monoclonal antibody targeting angiopoietin-like 3 (ANGPTL3) to treat dyslipidemia, or the SLC10A2 inhibitor odevixibat to treat cholestasis." (PMID 37277652, 2023). "The rational design of small molecules as ANGPTL3 inhibitors provides a potential approach for the management of dyslipidemia." (PMID 36293338, 2022). "Recently, emerging evidence has suggested that identifying compounds from natural phytochemicals that target ANGPTL3 is a feasible strategy for the prevention or treatment of dyslipidemia and ASCVDs." (PMID 36293338, 2022). "Firstly, GALT2 directly regulates HDL metabolism of mammalian; secondly, GALT2 act as an inhibitor of ANGPTL3, which causes dyslipidemia; thirdly, LPL activity is controlled by ANGPTL3, and LPL is a key enzyme in lipid metabolism." (PMID 36618414, 2022). "The objective of this study was to evaluate ANGPTL2 and ANGPTL3 in childhood obesity and their relationship with metabolic syndrome." (PMID 34422408, 2021). "The notable effect of ANGPTL3 on lipid metabolism has sparked interest in ANGPTL3 as a molecular target for the prevention or treatment of dyslipidemia and ASCVDs." (PMID 34298929, 2021). "As clinical studies continue to test the efficacy of targeting ANGPTL3 to treat dyslipidemia, investigations into the mechanisms and physiological roles of ANGPTL3-mediated lipase inhibition continue to be important." (PMID 34461133, 2021). "Targeting ANGPTL3 or ANGPTL8 represents promising strategies for the development of new treatment of dyslipidemia." (PMID 34356847, 2021). "Current studies in murine models have suggested that ANGPTL3 is a better pharmacological target than ANGPTL4 for the treatment of dyslipidemia and atherosclerosis." (PMID 34298929, 2021). "Clinical studies in patients with different forms of dyslipidemia have demonstrated that inactivation of ANGPTL3 using monoclonal antibodies or antisense oligonucleotides markedly lowers plasma LDL-C and triglyceride levels." (PMID 34581310, 2021). "ANGPTL3 (angiopoietin-like 3 protein) is a regulator of lipoprotein metabolism and has recently emerged as a novel therapeutic target to treat patients with dyslipidemia." (PMID 33691480, 2021). "These clinical studies indicate that pharmacological inactivation of ANGPTL3 shows efficacy and several potential benefits in patients with dyslipidemia." (PMID 34298929, 2021). "This review will summarize the current literature on the important role of ANGPTL3 in controlling lipoprotein metabolism and dyslipidemia, with an emphasis on anti-ANGPTL3 therapies as a potential strategy for the treatment of dyslipidemia and ASCVDs." (PMID 34298929, 2021).
dyslipidemia (continued). "In preclinical studies in various mouse models of dyslipidemia, silencing of ANGPTL3 using GalNAc-conjugated antisense oligonucleotides (ASO) significantly reduced plasma triglycerides, HDL-C, and LDL-C levels." (PMID 34581310, 2021). "In this study, we constructed GRSs composed 7 genetic variants (ANGPTL3 rs10889353, APOB rs7557067, GCKR rs780092, C2orf16 rs1919127, TRIB1 rs2954029, FADS1-FADS2-FADS3 rs174547, and APOA5 rs2266788) associated with dyslipidemia using GWAS studies." (PMID 33339179, 2020). "Numerous studies have already confirmed ANGPTL3 to be a promising target in the pharmacological therapy of dyslipidemia and CVD." (PMID 29334984, 2018). "Given that ANGPTL3, 4, and 8 proteins are secreted, their concentrations in circulation are reportedly associated with CVD risk factors such as dyslipidemia and impaired glycometabolism, although these associations vary between studies." (PMID 29538435, 2018). "Clinical trials are underway to further explore the potential of inactivating ANGPTL3 as a therapeutic target for dyslipidemia and CVD." (PMID 29334984, 2018). "Here, we review our current understanding of ANGPTL3, especially focusing on its role in the regulation of plasma lipid metabolism and its status as an effectively therapeutic target for dyslipidemia and CVD." (PMID 29334984, 2018). "Consistent with PCSK9, the significant effect of ANGPTL3 on plasma lipid levels has raised interest in ANGPTL3 as a therapeutic target for the treatment of dyslipidemia and CVD." (PMID 29334984, 2018). "Due to their role in regulating plasma lipid content and nutrient sensing, therapeutic modulation of the activity of ANGPTL3, 4 and 8 is currently under considerable investigation as potential targets in the treatment of dyslipidemia." (PMID 27733177, 2016). "Future research should investigate the feasibility of using ANGPTL3, ANGPTL4, and ANGPTL8 as biomarkers in DR and assess whether ANGPTL3-targeted therapies can improve disease progression in DR while managing dyslipidemia." (PMID 40559376, 2025). "Emerging agents such as ANGPTL3 and apoC-III inhibitors, as well as novel therapies like inclisiran and icosapent ethyl, offer promising avenues for further reducing cardiovascular risk in patients with persistent dyslipidemia after ACS." (PMID 41010649, 2025). "In addition, the degree of LDL-C and ApoB lowering achieved with both compounds was less than that observed with evinacumab in patients with severe hypertriglyceridemia or mixed dyslipidemia despite dramatic reductions in circulating ANGPTL3 levels." (PMID 40640392, 2025). "Further, an attenuation of angiopoietin-like 3 activity, an inhibitor of lipoprotein lipase (LPL), may be involved in the amelioration of the metabolic syndrome-associated dyslipidemia." (PMID 39596505, 2024). "In addition to PCSK9, targeting ANGPTL3 can be considered as avaluable therapeutic approach for dyslipidemia management." (PMID 39228490, 2024). "Thirdly, the current evidence on PCSK9 editing opens the stage for other genetically validated treatment targets in dyslipidemia such as lipoprotein(a), angiopoietin-like 3, and apolipoprotein CIII which can already be silenced with antisense-oligonucleotides and siRNA." (PMID 35050192, 2022). "ANGPTL3 could be involved in the development of dyslipidemia, as well as proteinuria, during PNS pathogenesis." (PMID 35399079, 2022). "Thus, nobiletin is a potential ANGPTL3 inhibitor for the regulation of lipid metabolism to ameliorate dyslipidemia and ASCVDs." (PMID 36293338, 2022). "Our findings suggest that nobiletin may serve as a potentially preventive or therapeutic agent for dyslipidemia and ASCVDs through downregulation of ANGPTL3 expression." (PMID 36293338, 2022). "In this study, we explored how ANGPTL3 impacts dyslipidemia during PNS development." (PMID 35399079, 2022). "Currently, Angptl3 is considered as a new potential target for the treatment of metabolic syndrome." (PMID 38149181, 2022).